TF (transferrin)
Diseases named in the same sentence as TF in open-access papers (continued):
Sharing a sentence is not in itself a finding about the gene and the disease.
iron deficiency (continued). "The increased transferrin saturation with nearly unchanged levels of soluble transferrin receptor could indicate a disturbed iron metabolism resulting in iron deficiency and in turn in reduced complex I activity." (PMID 36303924, 2022). "A study from Spain observed that a large percentage of genetic variation of serum transferrin was explained by two single nucleotide polymorphisms (SNPs) located in the transferrin (TF) gene, which affects the iron transport and leads to iron deficiency anemia risk in menstruating women." (PMID 34877231, 2021). "Patients with relative iron deficiency may have a TSAT of <20% because their bone marrow is stripping iron from the circulating transferrin faster than the transferrin can replenish it with iron released from stores." (PMID 33498292, 2021). "Because iron requires ceruloplasmin for oxidation and binding to transferrin (and total body stores of copper directly influence ceruloplasmin production), low serum copper levels are typically associated with microcytic anemia due to iron deficiency." (PMID 34434682, 2021). "In iron deficiency, decreased serum ferritin and transferrin saturation is expected." (PMID 34235219, 2021). "Patients in the two arms had similar age, preoperative hemoglobin levels, preoperative indices of iron deficiency, such as serum ferritin, serum iron, and transferrin saturation levels; a similar proportion of gender, race, and equal distribution of surgical sites, and surgical approach." (PMID 34567897, 2021). "Absolute iron deficiency is commonly defined by reduced ferritin levels (<30 μg/L), with low circulating iron and reduced binding of iron to the transport protein transferrin, as measured by low transferrin saturation (TSAT; <20%)." (PMID 33426933, 2021). "In fact, total iron and transferrin have been considered both redundant in iron deficiency anaemia and their values may overlap between healthy and iron deficient population." (PMID 33927552, 2021). "Iron deficiency was estimated as a low percentage of transferrin saturation, which was calculated as the ratio of iron to transferrin; both iron and transferrin are acute phase reactants, thus potentially interacting with many factors and not directly representing the nutritional status." (PMID 33026590, 2021). "The results showed that N. ceranae infection causes iron deficiency and upregulation of the A. mellifera transferrin (AmTsf) mRNA in honey bees, implying that higher expression of AmTsf allows N. ceranae to scavenge more iron from the host for its proliferation and survival." (PMID 33600478, 2021). "In our proteomic study, the expression levels of FTL and FTH1 were both decreased in the high myopia group, while the TF abundance was increased in the high myopia group compared to the low myopia group, indicating the potential impact of iron deficiency on the progression of myopia." (PMID 34660571, 2021). "As concluded by the Joint WHO/Centers for Disease Control and Prevention (CDC) Technical Consultation on the Assessment of Iron Status at the Population Level in 2004, transferrin saturation is characterized by lower sensitivity/specificity than serum ferritin in the prediction of iron deficiency." (PMID 34440936, 2021). "When the real-time rate of metabolism was tracked over a 6 h time period, TCA cycle substrate metabolism had the greatest recovery in metabolic rate, increasing from 0.44 fold during iron deficiency to 0.87 fold of the control level following transferrin rescue." (PMID 35050131, 2021). "To this end, hiPSC-CMs were exposed to the iron chelator deferoxamine (DFO) for 4 days to simulate ID and we used transferrin for 2 days to rescue the iron deficiency phenotype given that transferrin supplementation is routinely used in iron replacement therapy." (PMID 35050131, 2021).
iron deficiency (continued). "Erythropoietin (EPO) deficiency and/or resistance, iron deficiencies (resulting from reduced dietary intake, impaired enteral absorption, blood loss), and proteinuria (with loss of transferrin or EPO) are mechanisms leading to anemia development in patients with diabetic kidney disease." (PMID 34708130, 2021). "Here, we applied a novel mitochondrial function assay to assess the metabolism of a broad range of mitochondrial substrates in real time to study the effect of iron deficiency within hiPSC-CMs, and evaluate the extent of the metabolic rescue permitted by the supplementation of transferrin." (PMID 35050131, 2021). "CHr has been validated in literature as the strongest independent predictor of iron deficiency and iron deficiency anemia, when compared to other parameters (hemoglobin, ferritin, transferrin saturation, or mean corpuscular volume–MCV), both in adults and children." (PMID 33344383, 2020). "Serum iron, TIBC, and transferrin saturation are indexes of an adequate iron supply, but their utility as screening tools for iron deficiency is limited by several factors, such as the circadian rhythm (e.g., morning peak of serum iron and Tf saturation), diet, and oral contraceptive use." (PMID 32545511, 2020). "In iron deficiency, with very low transferrin iron saturation, iron absorption will result in a negligible amount of NTBI, whereas in iron-overload, characterized by highly saturated plasma transferrin, iron absorption will result in significant amounts of NTBI in the portal circulation." (PMID 32041196, 2020). "However, the two groups had comparable baseline levels of mean serum ferritin, CRP, and transferrin, mean transferrin saturation, and frequencies of anemia, iron deficiency, and iron deficiency anemia." (PMID 32724619, 2020). "Serum iron, transferrin and saturation of transferrin correspond well to circulating iron and may be used to recognize latent iron deficiency with diminished erythropoiesis." (PMID 32397525, 2020). "However, in addition to depleted iron stores, iron deficiency anemia can only be diagnosed in the presence of decreased serum iron, transferrin saturation, Hb, and MCV levels." (PMID 31121930, 2019). "(2013) have however stated that their findings might be better interpreted when complemented by an analyses of other parameters of iron deficiency such as transferrin, ferritin serum, and other biomarkers of inflammation." (PMID 30680185, 2019). "Patients with iron deficiency anemia have higher levels of transferrin than normal individuals." (PMID 30246592, 2018). "Low levels of iron, ferritin and transferrin are suggestive of iron deficiency anemia." (PMID 30237895, 2018). "In some cases, however, there may be adequate iron stores, with normal levels of serum ferritin, but insufficient iron is delivered by transferrin to meet cells' demand, a situation termed “functional iron deficiency”." (PMID 29744352, 2018). "As a consequence of chronic inflammation, patients with active IBD may show reduced levels of transferrin, which is contrary to the definition of patients with iron deficiency." (PMID 29342861, 2018). "In this study, patients with a low likelihood of iron deficiency (high ferritin, high transferrin saturation) were excluded, which may have yielded a more homogenous patient population." (PMID 29717382, 2018). "Iron deficiency is typically diagnosed on the basis of decreased transferrin saturation (i.e., <15%) and serum ferritin (<22 ng/mL), tests that effectively supplanted the historical gold standard for diagnosis, the absence of iron stores in bone marrow aspirate samples." (PMID 30042411, 2018). "JAK2 mutated patients exhibit iron-restricted erythropoiesis, with lower MCVs and higher sTfR1; systemic iron deficiency, with decreased serum iron, ferritin, and transferrin saturation; and expected lower serum Epo concentration relative to patients with wild-type JAK2." (PMID 30042411, 2018).
iron deficiency (continued). "The levels of transferrin have been shown to increase in iron deficiency anemia." (PMID 30246592, 2018). "In turn, iron deficiency might lead to the increase of manganese absorption which is harbored by the transferrin." (PMID 28521822, 2017). "cART improved CD4+ and CD8+ cell counts and their ratio, but this effect was significant only in group A. Only these patients had mild iron deficiency at T0 and showed higher transferrin and lower percentage of transferrin saturation than patients of group B, but differences disappeared with cART." (PMID 29258550, 2017). "Transferrin is an iron deficiency marker, superior to saturation-based indices and iron levels." (PMID 29226154, 2017). "Iron deficiency was defined as low transferrin saturation (TSAT) or ferritin levels." (PMID 29190715, 2017). "In addition, transferrin increases with iron deficiency, a condition present in some cases of malnutrition (Ingenbleek, Van Den Schrieck, De Nayer, & De Visscher, 1975)." (PMID 28031994, 2016). "Given these previous findings from different studies, we postulate that increased levels of transferrin could be a result of gastrointestinal blood loss and iron deficiency anemia that is associated with schistosomiasis." (PMID 27138990, 2016). "Furthermore, RDW is a more sensitive screening marker for iron deficiency than serum ferritin level, transferrin saturation, or serum iron level." (PMID 27154178, 2016). "Although the vitamin A-deficient rats (VAD) have presented systemic iron deficiency (lower serum iron concentration and transferrin saturation) like the iron-deficient groups (FeD and VAFeD), they showed iron retention in the spleen instead of a decrease as would be expected." (PMID 27551308, 2016). "Therefore, ACD is characterized by low serum iron, transferrin, and total iron binding capacity, by normal transferrin saturation, and by increased ferritin, the latter in contrast to iron deficiency anemia." (PMID 25878400, 2015). "Twelve months before diagnosis of PAI, mild normocytic anaemia was detected; Hb 89 g/L and biochemically confirmed iron deficiency (ferritin 12 μg/L [15–250 μg/L], transferrin saturation 6 % [10-35 %], transferrin 2.79 g/L [2.0-4.0 g/L], with normal B12 and folate levels." (PMID 26500000, 2015). "CONFIRM-HF was a multi-centre, double-blind, placebo-controlled trial that enrolled 304 ambulatory symptomatic HF patients with left ventricular ejection fraction ≤45%, elevated natriuretic peptides, and iron deficiency (ferritin <100 ng/mL or 100–300 ng/mL if transferrin saturation <20%)." (PMID 25176939, 2015). "Congenital apotransferrinemia, deficiency of serum TF, causes iron deficiency anemia." (PMID 26527688, 2015). "In an iron deficiency study in rat pups, in which a repletion group received an iron-adequate diet after 2 weeks of dietary ID treatment, brain iron and ferritin were normalized after 14 days, whereas brain transferrin was higher than in control animals." (PMID 26578919, 2015). "Indeed, a reduction of the transferrin saturation has been proposed to be indicative of iron deficiency only in conjunction with manifest anemia." (PMID 25514884, 2014). "Since neurons primarily acquire iron by TfR1, reduced TfR1 and increased ferritin expression in Irp2−/− brain would reduce transferrin-dependent iron uptake in parallel with an increase ferritin iron sequestration, eventually leading to cellular iron deficiency." (PMID 24896637, 2014). "Patients on treatment for indolent lymphoid malignancies, who had anemia [hemoglobin (Hb) 8.5–10.5 g/dL] and functional iron deficiency [transferrin saturation (TSAT) ≤20 %, ferritin >30 ng/mL (women) or >40 ng/mL (men)], were randomized to ferric carboxymaltose (1,000 mg iron) or control." (PMID 25373320, 2014).
iron deficiency (continued). "The diagnosis of iron deficiency is particularly challenging in patients with acute or chronic inflammatory conditions because most of the biochemical markers for iron metabolism (serum ferritin and transferrin ) are affected by acute phase reaction." (PMID 23555091, 2013). "Indeed, our animal data showed that mice fed 3.5 ppm iron had a transferrin saturation of < 20%, characterizing a mild iron deficiency." (PMID 23800380, 2013). "It is known that sports-induced inflammation is one of the main causes of iron deficiency in athletes and it is reported that inflammation increases ferritin (even in the presence of iron deficiency anemia) and transferrin levels and reduces sTfR concentrations." (PMID 23383348, 2013). "It is well established that in a situation of iron-deficiency the supply of iron to transferrin is compromised, increasing the serum levels of the protein while transferrin saturation and total iron binding capacity are decreased; this leads to ferritin stores being progressively diminished." (PMID 21978626, 2011). "In contrast to dietary intake, these SNPs are strongly associated with serum transferrin, and A carriers of rs3811647 present a reduction in iron transport to tissues, which might indicate higher iron deficiency anaemia risk." (PMID 21978626, 2011). "In the same study, human patients were designated as having anemia of inflammation in combination with iron deficiency if they had anemia, an associated inflammatory disease, and a transferrin saturation <16%, serum ferritin of <100 mcg/mL and sTfR/log ferritin >2." (PMID 20368776, 2010). "Here we show that both cp and ncp BVDV up-regulate transferrin (TF), a negative acute phase protein and a major iron transporter, causing iron overload and exacerbates disease (an animal with an increased serum transferrin level often suffers from iron deficiency anemia)." (PMID 20946620, 2010). "Transferrin saturation is less than 15% to 20% in iron deficiency, but expression of serum transferrin is reported to be downregulated by inflammatory cytokines, so may not reliably reflect iron deficiency when anemia is complicated by inflammation." (PMID 21490909, 2010). "In Gaucher disease, ferritin levels are generally elevated without other biochemical evidence of iron overload consistent with anaemia of chronic disease, whereas typical iron deficiency anaemia is characterized by low serum iron, low transferrin saturation and low ferritin levels." (PMID 17655728, 2007). "Our data thus suggests that SP1 or a related TF could be involved in regulating some of the genes in the 228 up-regulated cluster during iron-deficiency." (PMID 18005439, 2007). "This novel observation presents intriguing insights into the complex relationship between iron metabolism and cognitive functions in adolescents and suggests that transferrin saturation, a key indicator of iron deficiency, may influence the impact of iron on specific cognitive abilities." (PMID 39062151, 2024). "However, the transferrin saturation levels assessed in this study may also be indicative of iron deficiency anemia for TSAT levels ≤ 20%." (PMID 39062151, 2024). "However, in this study, absolute iron deficiency was defined as transferrin saturation and ferritin levels ≤ 20% and ≤ 200 ng/mL, respectively, whereas functional iron deficiency was defined as transferrin saturation and ferritin levels ≤ 20% and 200–800 ng/mL, respectively." (PMID 38941000, 2024). "Moreover, the transferrin/albumin ratio has also been used in iron deficiency diagnosis." (PMID 37513518, 2023). "Serum ferritin, CRP, transferrin saturation, and serum iron concentration should be tested to determine the presence of iron deficiency, whereas hemoglobin blood concentration, blood count, and other micronutrients should be assessed to diagnose iron deficiency anemia." (PMID 37111210, 2023).
iron deficiency (continued). "Low transferrin levels in presence of normal or low serum iron levels may contribute to iron deficiency anemia in alcoholics because insufficient transferrin level impairs iron delivery to the developing erythrocytes, and thereby restricts hemoglobin synthesis." (PMID 36214835, 2022). "Clinical studies reported that decreased levels of hemoglobin, free iron, transferrin, and ferritin might result in increased coagulability and indicate iron deficiency anemia, even if the platelet count and coagulation levels fell in the normal range in pediatric patients." (PMID 35682873, 2022). "As transferrin is the main iron binding protein in the blood, the fact that Fe-sulphate as well as >Your< Iron Syrup significantly increased its saturation in both sexes as compared to the Iron deficient Saline group strongly indicates a rescue of iron deficiency." (PMID 33922324, 2021). "In iron deficiency anemia, low serum levels of iron, transferrin saturation, and ferritin are observed; conversely, in inflammatory anemia, ferroportin-1 is inhibited due to high hepcidin levels, and iron is sequestered in its deposits which leads to high ferritin and low transferrin serum levels." (PMID 33924119, 2021). "Moreover, a new functional definition of iron deficiency, combining low ferritin levels with a reduced transferrin saturation, was proposed and proved strong efficacy in randomized clinical outcome trials of intravenous iron supplementation and prospective studies." (PMID 32215702, 2020). "However, biochemical signs of the disease, namely a mild anemia mimicking iron deficiency anemia because of microcytosis and low transferrin saturation, but with “paradoxical” hyperferritinemia, usually precedes the onset of clinical symptoms of many years and sometimes decades." (PMID 31024241, 2019). "Altogether, our data suggest that raised hepcidin levels in dialysis patients, due to several mechanisms including inflammation(IL-6)-induced synthesis and kidney retention, may contribute to a functional iron deficiency, as showed by the low serum iron and transferrin concentrations." (PMID 31296086, 2019). "However, this is followed by a reduction in blood iron, transferrin levels, and saturation and an increase in erythropoietin levels in the recovery period (3 or 15 days after race), consistent with the reported acute iron deficiency in marathon runners during this time period." (PMID 31244673, 2019). "In 70 patients, 30 (43%) had iron deficiency as determined by a serum iron < 10μmol-1 and transferrin saturation < 15% in females and <20% in males; in normal individuals levels of iron saturation of transferrin are 25% and above; 50% saturation indicates iron overload." (PMID 29904352, 2018). "In iron deficiency conditions, the Mn may harbor transferrin and access BG." (PMID 28521822, 2017). "Alcohol dehydrogenase transcripts were upregulated in the iron deficiency + Hb condition; they included aldehyde-alcohol dehydrogenase 2 (EHI_024240; a 2.3-fold increase), which known to be involved in the internalization of human transferrin and is regulated by iron." (PMID 25210888, 2014). "Genetic alterations in the gene coding for transferrin (TF), transmembrane serine protease 6 (TMPRSS6), and solute carrier family 40 member 1 (SLC40A1) are the primary sources of genetic diversity leading to iron deficiency." (PMID 40081160, 2025). "CKD patients diagnosed with RLS demonstrated notably lower serum ferritin, transferrin saturation, and serum iron levels, along with higher TIBC values, indicating both absolute and functional iron deficiency." (PMID 40677478, 2025). "ID: iron deficiency; LVEF: left ventricular ejection fraction; T: TSAT, transferrin saturation (%); F: ferritin (μg/L); CVM: cardiovascular mortality; HHF: hospitalization for heart failure; IV: intravenous." (PMID 40002874, 2025).